HGF (hepatocyte growth factor)
Diseases named in the same sentence as HGF in open-access papers (continued):
Sharing a sentence is not in itself a finding about the gene and the disease.
colon carcinoma (continued). "We tested the hypothesis that autocrine production of HGF by colon cancer cells confers resistance to EGFRi." (PMID 27121052, 2016). "The levels of HGF are increased in serum and in tumor tissues in colon cancer patients, particularly in patients with lymph node and liver metastasis, and are associated with poor survival of stage II and stage III colon cancer patients." (PMID 27121052, 2016). "HGF ameliorates mucosal injuries leading to inhibition of colon cancer development in mice." (PMID 27869219, 2016). "Furthermore, epithelial cells surrounding colon cancer stem cells secrete a hepatocyte growth factor (HGF) and maintain high Wnt activity in colon cancer stem cells, but also induce the activation of Wnt in differentiated cancer cells." (PMID 25437036, 2013). "Previous studies have shown that MACC1 acts as a transcription activator for c-MET and as a key regulator of HGF-c-MET signaling pathway in colon cancer, promoting proliferation, invasion and HGF-induced scattering of colon cancer cells and xenograft growth and metastasis in vivo." (PMID 23497677, 2013). "Interestingly, in the present study we detected a selective up-regulation of FL-L1CAM upon exposure of SKOV3ip-lacZ human ovarian carcinoma cells to TGF-β1and of HCT-116 human colon carcinoma cells to HGF, which are known pro-metastatic factors." (PMID 21541352, 2011). "Notably, treatment of colon carcinoma cells with the MEK1/2 inhibitor PD184352 was shown to inhibit HGF-induced cell scattering and to reduce their invasive properties." (PMID 19014680, 2008). "HGF from cultured myogenic cells may have influenced the differential responses by endothelial and myogenic cells to Sema3A and 3F, as found in studies of human colon cancer in a mouse transgenic strain." (PMID 29854302, 2018). "Indeed, the HGF/Met axis sustains the stem cell phenotype in glioblastoma and colon cancer." (PMID 26987019, 2016). "It is also observed that senescent colon cancer cells can promote EMT in adjacent cells through IL-6, MMP-3, FGF, and HGF, potentially facilitating tumor metastasis." (PMID 41614944, 2026). "To explore the potential signaling axis (HGF/MET/MYC) between CAFs and CRC, we conducted further validation using colon cancer cell lines HCT-116 and COLO205." (PMID 41234356, 2025). "In colon cancer, ERK/MAPK signaling pathway was involved in the effects of hepatocyte growth factor (HGF) of promoting proliferation and regulating cell cycle and apoptosis of cancer cells." (PMID 35264195, 2022). "The aim of this study was to investigate the role of the HGF/c-MET axis in the proliferation and metastasis in colon cancer." (PMID 35874635, 2022). "MACC1 is a key regulator of the hepatocyte growth factor (HGF) receptor and has mainly been identified as an independent prognostic factor for metastasis formation and metastasis-free survival in colon cancer." (PMID 37304008, 2022). "MACC1, a critical modulator of the HGF/MET signaling pathway, was revealed to predict colon cancer metastasis." (PMID 34939526, 2022). "This experiment showed that there was also an upstream-downstream relationship between MACC1 and c-MET in colon cancer cells and tissues, both of which formed the MACC1/HGF/c-MET axis." (PMID 35874635, 2022). "Specifically, inhibition of the MACC1/HGF/c-MET axis contributes to the treatment and prognosis of colon cancer and also helps to suppress the proliferation and invasion of colon cancer cells." (PMID 35874635, 2022). "Therefore, HGF/SF stimulation of colon cancer cells along the invasive front will trigger the acquisition of quasi-mesenchymal characteristics and the AS-driven switch from CD44v6 to CD44s, the latter unable to bind HGF and as such controlling the extension of EMT activation." (PMID 36346211, 2022). "The exploration of the MACC1/HGF/c-MET pathway in colon cancer provides favorable evidence for drug targeting of MACC1 and regulation of MACC1/HGF/c-MET in colon cancer therapy." (PMID 35874635, 2022).
colon carcinoma (continued). "Similar to CCL20, HGF induces migration, autofeedback CCL20 secretion, and ERK1/2 phosphorylation in the colon cancer cells." (PMID 34853656, 2021). "In this study, we show that CCL20 stimulation induces hepatocyte growth factor (HGF) production and phosphorylation of its receptor c-Met by colon cancer neoplastic epithelial cells." (PMID 34853656, 2021). "Metastasis associated with the colon cancer-1 (MACC1) gene, which plays an important role in regulating the hepatocyte growth factor (HGF)/MET signaling pathway, is recognized as a prognostic biomarker for colon cancer." (PMID 34072650, 2021). "For instance, growth factors like hepatocyte growth factor (HGF), secreted by the stromal myofibroblasts, activate the Wnt-signaling in a subset of colon cancer cells that maintain the CSC phenotype." (PMID 32626705, 2020). "CAF-derived HGF is proposed to promote the formation of the CSC niche and tumorigenicity by activating the Wnt signaling pathway in differentiated colon cancer cells." (PMID 30356678, 2018). "High levels of HGF were also observed in the serum and tumor tissue of stage II and III colon cancer patients, and especially in patients with lymph node and liver metastasis." (PMID 30214428, 2018). "Intrinsic and hepatocyte growth factor (HGF) -induced cell motility in human HT29 and HCA7 colon carcinoma cells was assessed carrying out cell scattering and scratch wound healing assays using time-lapse microscopy." (PMID 27270323, 2016). "The levels of endogenous inhibitors of HGF activation, HAI-1, are reduced in colon cancer tissues compared to normal mucosa." (PMID 27121052, 2016). "Together these data demonstrate that SRI31215 inhibits autocrine or paracrine HGF/MET signaling and thus averts the resistance of colon cancer cells to EGFRi." (PMID 27121052, 2016). "More direct evidence for the role of HGFA in cancer tissue was reported in colon cancer, myeloma, and diffuse large B-cell lymphoma, in which a neutralizing antibody against HGFA suppressed HGF/SF activation." (PMID 25268161, 2014). "MACC1 functions as a key activator of the HGF/c-MET signaling pathway, promoting colon cancer cell proliferation, invasion and metastasis in culture, and the growth and metastasis of tumors in xenograft models." (PMID 25009663, 2014). "Metastasis-associated in colon cancer-1(MACC1), a newly identified key regulator of hepatocyte growth factor(HGF)-MET signaling, predicts colon cancer metastasis." (PMID 23573286, 2013). "A mechanistic study showed that TNC promotes colon carcinoma cell invasion via the epidermal growth factor receptor (EGFR) and hepatocyte growth factor (HGF) signaling pathways; TNC secreted by CAFs activates EGFR and HGF." (PMID 22481923, 2012). "PRL-3 expression was reported to be regulated at transcriptional level by mitogenic cytokines, such as IL-6, IL-21, HGF or IGF-1 in myeloma cell lines, or as TGF-β in colon cancer cell lines." (PMID 21466710, 2011). "Overexpression of Rab31 in cancer-associated fibroblasts (CAFs) enhances cell migration in an HGF/MET-dependent manner in colon cancer cells, indicating a key role for Rab31-expressed CAF in the colon cancer cell migration by mediating paracrine secretion of HGF." (PMID 38695990, 2024). "In contrast, IQGAP1 promotes HGF-stimulated colon cancer cell invasion, implying that the functions of IQGAP1 in HGF/MET signaling may be cell-dependent." (PMID 37071417, 2023). "On the contrary, we found a negative correlation between HHLA2 tumor concentration factor 1 from principal component analysis containing: HGF, M-CSF, b-NGF, SCGF-b, IL-7, FGFbasic, G-CSF, PDGF-bb, VEGF, GM-CSF, and trophic factors, which can be produced by colon tumor cells." (PMID 36982953, 2023).
colon carcinoma (continued). "Metastasis associated in colon cancer 1 (MACC1) gene was first identified in 2009 as a key regulator of hepatocyte growth factor-mesenchymal-epithelial transition factor (HGF-MET) signaling and the expression of MACC1 in tumor specimens is an independent prognostic factor for colon cancer." (PMID 38021160, 2023). "Then, we identified the MACC1/HGF/c-MET axis in colon cancer and tried to explore whether this axis could interfere with colon cancer invasion and metastasis by regulating MACC1 or by blocking the expression of downstream c-MET." (PMID 35874635, 2022). "Overexpression of RAB31 in CAFs promoted colon cancer cell migration in an HGF/MET-dependent manner, suggesting a role for CAF-expressed RAB31 in the migration of colon cancer cells through regulating paracrine secretion of HGF." (PMID 33072555, 2020). "We propose that in colon cancer, increased RAB31 expression in CAFs may contribute to tumor progression by regulating the secretion of HGF in the tumor stroma." (PMID 33072555, 2020). "We demonstrated previously that SRI31215 effectively inhibits HGF-dependent MET activation, proliferation, epithelial-mesenchymal transition and migration of cancer cells and overcomes fibroblast-mediated resistance to EGFR inhibitors in colon cancer cells." (PMID 28968967, 2017). "SRI31215, a novel inhibitor of pro-HGF activation, blocked signaling between tumor-promoting fibroblasts and colon cancer cells and overcame fibroblast-mediated resistance to EGFR inhibitors in colon cancer cells." (PMID 28968967, 2017). "In the present study, we focused on the impact of the HGF/MET pathway on Chk1 activity, taking into account previous findings of a role of the MET pathway in regulation of cell proliferation and cetuximab resistance in colon cancer cells." (PMID 28573382, 2017). "In this study, we investigated the anti-carcinogenic activity and underlying molecular mechanisms of cloudberry extract by studying its effects on HGF-induced cell migration using human HT29 and HCA7 colon carcinoma cells in scattering and scratch wound healing assays." (PMID 27270323, 2016). "In addition, our study indicates that dual inhibition of HGF and EGFR precludes primary and acquired, fibroblast-mediated, resistance to EGFRi in colon cancer cells." (PMID 27121052, 2016). "The statement is additionally supported by the fact that HGF-MET axis maintains cancer stem cells functions in different tumor types, such as glioblastoma, head and neck squamous cell carcinoma, pancreatic, colon cancer or cervical carcinoma." (PMID 26384300, 2015). "We applied a limited candidate gene approach (EGFR, HGF ad MET by immunohistochemistry), array CGH, and genomic sequencing to compare CB42 to other propagation-incapable, β-Catenin-driven primary colon tumors to identify a series of candidate genes that correlated with propagation/metastasis." (PMID 25162504, 2014). "In a colon cancer model, REG4 was induced by growth factors, including transforming growth factor-alpha, epidermal growth factor (EGF), basic fibroblast growth factor and hepatocyte growth factor." (PMID 23342005, 2013). "In colon cancer cells, MAPK signaling could be hyperactive by transfection of MACC1, and HGF-induced cell scattering mediated by MACC1 could be abrogated by MEK specific inhibitors, whereas not by PI3K specific inhibitors." (PMID 21923915, 2011). "MACC1 may act as a key regulator of the HGF/c-MET pathway, leading to distant metastases in colon cancer." (PMID 21955323, 2011). "Moreover, hepatocyte growth factor (HGF), the ligand for c-Met, can restore the CSC phenotype in more differentiated colon cancer cells and seems to play a major role in maintaining a CSC state." (PMID 21311095, 2010). "Interestingly, unlike CCL20, HGF does not induce proliferation of colon cancer cells, and CCL20-dependent cell proliferation is not blocked by direct HGF inhibition." (PMID 34853656, 2021).
colon carcinoma (continued). "To test whether PIPKIγ regulates the migration of HCT116 colon cancer cells, we employed time-lapsed wound-healing assays to examine the migration of HCT116 cells expressing EGFP-PIPKIγ and –PIPKIγK188,200R, respectively, in the presence of HGF." (PMID 21931851, 2011). "We used HGF-producing RKO cells which, despite carrying WT KRas, do not respond to cetuximab and represent a large proportion of colon cancer patients with WT KRas that fail to respond to EGFRi." (PMID 27121052, 2016). "Therefore, we selected two colon cancer cell lines that are dependent on the ATR/Chk1 pathway, and observed that Chk1 phosphorylation levels gradually increased after HGF stimulation; this increase was not dependent on HGF concentration." (PMID 28573382, 2017).
colorectal cancer (92 papers, 1998 to 2025). A primary or metastatic malignant neoplasm that affects the colon or rectum. "ESM1 was the protein with the strongest inverse association with colorectal cancer (OR: 0.59 95% CI 0.43–0.80), closely followed by HGF (OR: 0.60 95% CI 0.42–0.85)." (PMID 33664295, 2021). "In colorectal cancer, tumor-associated myofibroblasts secreted factors such as HGF that stimulated Wnt signaling, which subsequently gave rise to cancer stem-like cells and tumorigenesis." (PMID 29991717, 2018). "Hepatocyte growth factor (HGF) is a crucial factor associated with development, progression and metastasis of colorectal cancer (CRC)." (PMID 28423584, 2017). "A complex of MET, CD44 variant 6 and the MET ligand HGF has been identified in the colorectal cancer cell line HT-29 and has been demonstrated as being essential for MET activation." (PMID 26243458, 2016). "We evaluated 45 common and putative functional variants of CYP19A1 and circulating levels of HGF among 260 postmenopausal women who later developed colorectal cancer from the Women's Health Initiative Observational Cohort." (PMID 22848710, 2012). "This is supported by a report showing that elevated c-Myc expression via β-catenin phosphorylation, in response to HGF stimulation in colorectal carcinoma cells, is associated with a more tumorigenic and metastatic phenotype." (PMID 22962849, 2012). "HGF’s capacity to stimulate angiogenesis in tumors is probably the reason why elevated blood levels of the hormone have been linked to the advancement of cancer, particularly colorectal cancer." (PMID 39590368, 2024). "Apart from HGF detected in tumor tissue, elevated HGF in blood expression was associated with high risk for metastasis and inferior OS in breast, bladder, gastric, esophageal, colorectal cancers, ovarian cancer and myeloma." (PMID 37828456, 2023). "In fact, the HGF/c-Met pathway has been implicated in the metastatic process of colorectal cancer." (PMID 34853656, 2021). "Furthermore, the importance of this pathway is corroborated as overexpression of HGF and c-Met in the colorectal cancer microenvironment is associated with poor clinical outcome." (PMID 34853656, 2021). "Colorectal cancer is known to be associated with oncogenic dysregulation of the HGF/c-Met pathway." (PMID 34853656, 2021). "In stromal cells, it is reported that hepatocyte growth factor (HGF) secreted by myofibroblasts could activate nuclear β-catenin activity and thereby affect stemness features which are associated with chemoresistance in colorectal cancer cells." (PMID 32258160, 2020). "As treatments, it has been reported that the downregulation of HGF/MET signaling by siRNA of MET or the expression of HGF-antagonist has achieved the suppression of liver metastasis in colorectal cancer." (PMID 40076928, 2025). "MACC1 promotes the development of colorectal cancer by activating the HGF/c-MET signaling pathway, which is consistent with the high expression of MACC1 in our sequencing results." (PMID 40740230, 2025). "For example, COL1A1 has been reported to be linked with immune infiltrating cells, and RAB31 is expressed in CAFs, contributing to the malignant potential of colorectal cancer through the secretion of HGF in the tumor stroma." (PMID 38557819, 2024). "In a mouse model of liver metastasis due to colorectal cancer, Treg numbers were elevated, and the hepatocyte growth factor/hepatocyte growth factor receptor signaling pathway was up-regulated." (PMID 35871700, 2023). "The roles of MACC1 in cancer invasion, epithelial-to-mesenchymal transition, HGF-triggered scattering of cancer cells and metastasis have been first identified in colorectal cancer in vitro and in vivo, and subsequently described in other types of cancers." (PMID 37496665, 2023).